ENSG00000249141 (novel protein)
Gene: Protein-coding gene on chromosome 6 (166,858,094 to 166,956,124, reverse strand). Ensembl gene ENSG00000249141.
Genetic constraint (gnomAD): Loss-of-function variants: 9 observed, 11.59 expected, observed/expected ratio (o/e) 0.78, 90% interval 0.47 to 1.35. Missense variants: 106 observed, 110.48 expected, observed/expected ratio (o/e) 0.96, 90% interval 0.82 to 1.13. Synonymous variants: 35 observed, 38.85 expected, observed/expected ratio (o/e) 0.9, 90% interval 0.69 to 1.19.